USP4 (ubiquitin specific peptidase 4)
Diseases named in the same sentence as USP4 in open-access papers (continued):
Sharing a sentence is not in itself a finding about the gene and the disease.
cancer (continued). "Therefore, the present review will give a comprehensive overview about its regulatory mechanisms, involved signaling pathways, roles in pathological and physiological process, especially in different cancers to raise further studies of USP4 in extensive cancer therapy and clinical application." (PMID 32669974, 2020). "And the cancer target potential and clinical application value of USP4 may be underestimated." (PMID 32669974, 2020). "However, the function and mechanism of USP4 in cancer development is controversial." (PMID 29396555, 2018). "However, the mechanism by which USP4 mediates HDAC2 de-ubiquitination contributing to cancer remains unclear." (PMID 30071870, 2018). "We speculated that USP4 overexpression may act as a cancer promoter in HCC." (PMID 29396555, 2018). "Prior research has established that USP4 promotes TGF-β signaling and synergizes with AKT signaling to enhance the invasion and migration of cancer cells." (PMID 39393052, 2024). "In terms of treatment, USPs can be used as cancer therapeutic targets, such as inhibitors of USP1, USP4, USP7, USP9X, and USP33 for prostate cancer, lung cancer, breast cancer, and hematological malignancies, among others." (PMID 38613804, 2024). "USP4 is a member of the USP family that can function as either a tumor promoter or a tumor suppressor, depending on cancer type." (PMID 37624791, 2023). "Therefore, both USP15 and USP4 may be considered important prognostic biomarkers in human cancers." (PMID 35027535, 2022). "For example, there are some DUBs that are only identified in the cancer cells like USP3, USP4, and OTUD7B." (PMID 33718328, 2021). "It has been reported that USP4 can deubiquitinate and stabilize TRAF2/TRAF6 to inhibit TNFα-induced cancer cell migration." (PMID 32549341, 2020). "USP4 has previously been confirmed to target TRAF2 and TRAF6 for deubiquitination and it has been established that USP4 inhibits TNFα-induced cancer cell migration." (PMID 30194441, 2018). "The authors also showed that ubiquitin-specific protease 4 (USP4) interacts with PRL-3 and decreases the levels of its ubiquitinated product preventing PRL-3 degradation in human cancer cells." (PMID 27911713, 2016). "Ubiquitin-specific protease USP4 is emerging as an important regulator of cellular pathways, including the TGF-β response, NF-κB signalling and splicing, with possible roles in cancer." (PMID 25404403, 2014). "These tumor suppressor genes downregulated in cancer are PDCD4-AS1, RNF40, USP4, and ST13P5." (PMID 41347211, 2025). "Next, we examined whether the cancer progression ability of USP15 and USP4 is allied with SRSF1 alternative splicing." (PMID 35027535, 2022). "USP4, USP7, and USP47 are DUBs that are abnormally overexpressed in many cancers." (PMID 35884836, 2022). "Accordingly, USP4 and PRL-3 protein levels positively correlate in clinical samples and cancer cell lines, but not in the mRNA levels, confirming that the USP4-dependent regulation of PRL-3 protein levels is a posttranslational event." (PMID 27911713, 2016). "Finally, if small-molecule inhibitors of USP4, USP15, and/or USP11 are developed, it will be interesting to pursue their potential in cancer therapy." (PMID 26455393, 2015).
cancer (continued). "Secondly, it reduces Ubiquitin Specific Peptidase 4 (USP4) expression, leading to the degradation of ELAV Like RNA Binding Protein 1 (ELAVL1) protein and subsequently increasing Rho GDP Dissociation Inhibitor Alpha (ARHGDIA) levels, promoting cancer cell invasion and migration." (PMID 38711100, 2024). "Moreover, USP4 and its paralog USP15 play both promoting and suppressing roles in cancer." (PMID 33681193, 2021). "In low USP15 and USP4 upon depletion, SRSF1 is down-regulated with substantial retention of the C-terminal intron sequences recognized as an altered isoform SRSF1-3, which is degraded by NMD and thus do not show any effects on cancer cell phenotype." (PMID 35027535, 2022).
tumor (40 papers, 2014 to 2025). "Further investigation is imperative to elucidate the precise molecular mechanisms underlying the tumor-promoting functions of USP4 in PTC." (PMID 39393052, 2024). "In summary, both in vitro and in vivo findings in this study reveal a critical mechanism for regulation of lung tumorigenicity and aggression involving Snail1-mediated epigenetic downregulation of USP4 triggered in part by tumor associated macrophages." (PMID 31936290, 2020). "And in the small tumor (diameter ≤ 5 cm) and early stage (stages 1 and 2) subgroups, higher USP4 expression was also associated with a better survival." (PMID 32669974, 2020). "In the present study, we found that USP4 was significantly upregulated in HCC tumor tissues and the high expression of USP4 was associated with distant metastasis and poor survival in patients." (PMID 30335615, 2018). "Taken together, our results elucidate that USP4 is highly expressed in HCC and promotes the tumor invasion and metastasis, the underlying mechanism is that USP4 directly interacts with and deubiquitinates TGFR-1 to increase TGF-β signaling-Induced EMT." (PMID 30335615, 2018). "Additionally, we observed a positive correlation between USP4 expression levels and critical clinical parameters, including tumor size, TNM stage, BRAF mutation, decreased recurrence-free survival time, and decreased overall survival time." (PMID 39393052, 2024). "Knocking down USP4 stimulates the production of ISGs, increases the anti-tumor activity of CD8+ T cells, and improves immunotherapy effectiveness." (PMID 39223632, 2024). "In colorectal cancer (CRC) with a microsatellite stable (MSS) phenotype, USP4 expression is upregulated, impairing the anti-tumor immune response." (PMID 39223632, 2024). "Collectively, these findings indicate that USP4-facilitated BRCA1 stabilization potentially plays a tumor-suppressive role in breast carcinogenesis." (PMID 38734703, 2024). "Statistical analysis revealed that high expression of USP4 was correlated with tumor size, invasion depth, and lymph node metastasis." (PMID 37949874, 2023). "Next, tumor xenograft models were established in nude mice to determine the effects of USP4 on ESCC growth." (PMID 37949874, 2023). "On the other hand, USP4 can establish its tumor suppressive role by inhibiting cell proliferation or promoting cell apoptosis in neck squamous cell carcinoma and breast cancer." (PMID 37624791, 2023). "In contrast, depletion of USP4 significantly inhibited proliferation, migration, and invasion abilities in vitro and suppressed tumor growth and metastasis in vivo." (PMID 37949874, 2023). "Consistently, USP4 silencing repressed tumor growth and metastasis in an ESCC nude mouse model in vivo." (PMID 37949874, 2023). "U0126, a specific inhibitor of MEK/ERK, counteracted the promoting effects of USP4 overexpression on cell proliferation, metastasis, and tumor growth." (PMID 37949874, 2023). "FBXO3 functions as a USP4 binding partner to protect USP4 from degradation, which in turn leads to stabilization of Twist1, thereby promoting cell migration and tumor metastasis." (PMID 38134227, 2023). "Tumor samples from a total of 113 patients (TMA dataset) were analyzed for USP4 protein levels semi-quantitively using immunohistochemistry." (PMID 37308746, 2023). "USP4 expression was slightly upregulated in primary tumor tissues in comparison with normal tissues." (PMID 37949874, 2023). "In vivo, treatment with U0126 further enhanced the suppression of tumor growth induced by downregulation of USP4." (PMID 37949874, 2023). "In breast cancer, USP4 directly interacts with and deubiquitinates TβRI and promotes the proliferation of tumor cells." (PMID 36969062, 2023). "The influences of USP4 expression levels on tumorigenesis and tumor growth were further investigated in mice inoculated with USP4 knockdown or control LLC cells." (PMID 31936290, 2020).
tumor (continued). "Studies of USP4 knockout mice revealed that USP4 upregulates tumor growth in an mTORC1-dependent manner." (PMID 32486221, 2020). "A wealth of evidence strongly suggests that USP4 functions as a tumor-promoting protein, as exemplified by the ability of USP4 to promote tumorigenesis via deubiquitinating and stabilizing ARF-BP1, β-catenin and TGF-βRI." (PMID 32549341, 2020). "A higher tumor development rate and a faster growth rate was observed for tumors derived from USP4 knockdown cells." (PMID 31936290, 2020). "By counting the number of tumors in mouse colons, we found that USP4−/− mice developed fewer tumor colonies compared with WT mice, whereas the body weight loss of WT mice was higher than that of USP4−/− mice." (PMID 30514904, 2019). "In summary, these data indicate that both RNF152 and USP4 play important roles in tumor growth via regulating mTORC1 activation." (PMID 30514904, 2019). "In summary, these results demonstrated that USP4 expression contributes to HCC cell invasion and metastasis, suggesting that USP4 functions as a tumor promoter in HCC." (PMID 30335615, 2018). "Ubiquitin-specific protease 4 (USP4) is a member of the deubiquitinating enzyme family, which plays an important role in human tumor diseases." (PMID 29396555, 2018). "Immunohistochemical staining showed that USP4 was significantly upregulated in tumor tissues compared with matched surrounding tissues." (PMID 30335615, 2018). "The results showed that increased USP4 expression was highly correlated with histological differentiation (P = 0.002), tumor size (P = 0.003), tumor number (P = 0.043), vascular invasion (P = 0.003), and serum alpha-fetoprotein (AFP) levels (P = 0.024)." (PMID 29396555, 2018). "Using IHC staining, we found that tumor xenografts with USP4 knocked down showed lower Ki-67 expression, a cell proliferation marker, than controls." (PMID 29396555, 2018). "In the present study, tissue microarrays showed that USP4 was significantly upregulated in HCC tumor tissues compared with matched surrounding tissues." (PMID 30335615, 2018). "Then, multivariate analysis revealed that USP4 expression, vascular invasion, and tumor size (P < 0.05 for all) were independent prognostic factors for OS and cumulative recurrence." (PMID 29396555, 2018). "Mouse USP15 shares 75.5% sequence similarity with the mouse USP4, named Unp, which has been identified as a proto-oncogene able to promote tumor initiation when overexpressed in nude mice." (PMID 28245560, 2017). "Our findings that miR-148a dysregulation correlated with USP4 in the tumor samples and that patients having high USP4 showed a tendency to have high TNM stage (TNM stage II-III) support the role of USP4 in the transition of HCC to a malignant phenotype." (PMID 24798342, 2014). "To determine the effect of USP4 or S1P1 overexpression on the progression of HCC in association with miR-148a dysregulation, we used a panel of tumor-derived cell lines and xenograft animal model." (PMID 24798342, 2014). "In this study, we observed a marked upregulation of USP4 expression in PTC tumor tissues." (PMID 39393052, 2024). "Together, these findings indicate that USP4 promotes cell proliferation and tumor growth in ESCC." (PMID 37949874, 2023). "Moreover, high expression of USP4 was predominantly detected in 70.2% (125/178) of the ESCC tumor specimens, whereas only 20.0% (8/40) of the corresponding para-cancerous tissues showed high expression (P < 0.001)." (PMID 37949874, 2023). "Here, USP4 expression was found to be markedly upregulated in ESCC tumor tissues and cells." (PMID 37949874, 2023). "USP4 is significantly upregulated in tumor tissues compared to matched non-tumor tissues in HNSCC." (PMID 36613989, 2022). "This highlights the potential therapeutic role of USP4 phosphorylation in tumour progression." (PMID 34177595, 2021).
tumor (continued). "Moreover, we also found that the knockdown of USP4 effectively alleviated METTL3 decifiency-induced suppressed xenograft tumor formation." (PMID 34335955, 2021). "Moreover, we observed that USP4 knockdown effectively alleviated METTL3 knockdown-induced inhibited xenograft tumor growth." (PMID 34335955, 2021). "Tumor-suppressing role of USP4 can also be modulated by miRNAs." (PMID 32669974, 2020). "The tumor-promoting role of USP4 also relates with HDAC2 activation." (PMID 32669974, 2020). "Agents which can block this Snail1 and USP4 mediated positive feedback loop might be able to inhibit tumor progression and therapeutic resistance." (PMID 31936290, 2020). "In addition, USP4 inhibitor, Vialinin A, inhibited tumor growth and reduced the phosphorylation level of p-S6." (PMID 30514904, 2019). "Meanwhile, knockdown of USP4 led to reduced tumor size, as well as reduced expression level of p-S6, which could be rescued by the expression of Rheb-K8R." (PMID 30514904, 2019). "Consistently, mTORC1 activity was decreased in the tumor samples from USP4−/− mice." (PMID 30514904, 2019). "USP4 has different partners in different tumor types, which results in distinct functions." (PMID 30335615, 2018). "The results confirmed that USP4 is overexpressed in tumor tissues (P < 0.01)." (PMID 29396555, 2018). "Next, Kaplan-Meier analysis presented that in tumor tissues, but not surrounding tissues, high expression of USP4 was significantly associated with a lower survival rate." (PMID 30335615, 2018). "Our observation that USP4 is recruited by TRPS1 to de-ubiquitinate HDAC2 and silence USP4, resulting in inhibition of tumor cell growth by TRPS1, is consistent with these notions elucidating the underlying molecular details of the oncogenic function of the TRPS1/HDAC2/USP4 axis in tumor growth." (PMID 30071870, 2018). "Increasing evidence has confirmed that USP4 plays an important role in tumor progression." (PMID 29396555, 2018). "Besides, USP4 expression was positively correlated with the expression of Ki67 (Tumor proliferation marker) and CD34 (microvessel marker)." (PMID 30335615, 2018). "USP4 has been proved as a versatile regulator in terms of tumour biology." (PMID 29542252, 2018). "Finally, total proteins were extracted from fresh HCC tissues and matched surrounding tissues, and western blots confirmed that USP4 was overexpressed in tumor tissues compared with matched surrounding tissues (14/20=70%)." (PMID 30335615, 2018). "In addition, we verified the inverse relationship between miR-148a and USP4 (or S1P1) in a tumor xenograft model." (PMID 24798342, 2014). "USP4 may act as a tumour suppressor protein in some tumours." (PMID 36969062, 2023). "Thus, USP4 is a promising tumor biomarker and therapeutic target for ESCC." (PMID 37949874, 2023). "USP4-mediated regulation of tumor metastasis may be context-dependent." (PMID 38134227, 2023). "However, high USP4 expression in tumor tissues was correlated with a favorable OS." (PMID 32669974, 2020). "Moreover, AKT-mediated USP4 phosphorylation can abolish the ubiquitination of Rheb and then stabilize it, which activate the mechanistic target of rapamycin complex 1-mediated signaling pathways, thus influenced tumor growth." (PMID 32669974, 2020). "Moreover, USP4 was up-regulated in mesenchymal-phenotype liver-tumor cells." (PMID 24798342, 2014). "The tumor suppressors PDCD4-AS1, RNF40, USP4, and ST13P5 are good candidates for knock-in experiments to see if an increase in expression causes less or more proliferation." (PMID 41347211, 2025). "Among these, USP11—a deubiquitinating enzyme structurally and sequentially similar to USP4 and USP15—was notably overexpressed in the tumor tissues of 25 CRC patients, compared to USP4 and USP15." (PMID 41419456, 2025).